GRSF1 (G-rich RNA sequence binding factor 1)
Description:
Regulator of post-transcriptional mitochondrial gene expression, required for assembly of the mitochondrial ribosome and for recruitment of mRNA and lncRNA. Binds RNAs containing the 14 base G-rich element. Preferentially binds RNAs transcribed from three contiguous genes on the light strand of mtDNA, the ND6 mRNA, and the long non-coding RNAs for MT-CYB and MT-ND5, each of which contains multiple consensus binding sequences. Involved in the degradosome-mediated decay of non-coding mitochondrial transcripts (MT-ncRNA) and tRNA-like molecules. Acts by unwinding G-quadruplex RNA structures in MT-ncRNA, thus facilitating their degradation by the degradosome. G-quadruplexes (G4) are non-canonical 4 stranded structures formed by transcripts from the light strand of mtDNA.
Tractability: PROTAC: ubiquitination databases record sites on it; its protein half-life has been measured.
Gene: Protein-coding gene on chromosome 4 (70,815,783 to 70,839,903, reverse strand). Ensembl gene ENSG00000132463.
Subcellular location: Mitochondrion matrix (Isoform 1); Cytoplasm (Isoform 2)
Subcellular location (Human Protein Atlas): Mitochondria
Pathways (Reactome):
Disease: Viral mRNA Translation
Metabolism of RNA: Mitochondrial RNA degradation
Gene Ontology:
Molecular function: mRNA binding; protein binding; RNA binding; G-quadruplex RNA binding; nucleic acid binding
Biological process: positive regulation of mitochondrial RNA catabolic process; mitochondrial RNA catabolic process; regulation of RNA splicing
Cellular component: cytoplasm; mitochondrial matrix; mitochondrial nucleoid; mitochondrion; ribonucleoprotein granule; nucleoplasm; ribonucleoprotein complex
Genetic constraint (gnomAD): Loss-of-function variants: 26 observed, 24.51 expected, observed/expected ratio (o/e) 1.06, 90% interval 0.78 to 1.47. The synonymous counts are far from expectation, so gnomAD's model fits this gene poorly and the ratio says little. Missense variants: 473 observed, 362.4 expected, observed/expected ratio (o/e) 1.31, 90% interval 1.21 to 1.41. Synonymous variants: 204 observed, 148.19 expected, observed/expected ratio (o/e) 1.38, 90% interval 1.23 to 1.55.
Homologues: Orthologues: chimpanzee GRSF1 (97% identical), dog GRSF1 (93% identical), pig GRSF1 (91% identical), mouse Grsf1 (91% identical), macaque GRSF1 (90% identical), rat Grsf1 (90% identical), guinea pig GRSF1 (82% identical), rabbit GRSF1 (77% identical), tropical clawed frog grsf1 (42% identical), Drosophila melanogaster glo (26% identical), Caenorhabditis elegans sym-2 (22% identical), Drosophila melanogaster fus (22% identical), and 2 more. Paralogues in human: HNRNPH1 (32% identical), HNRNPH2 (31% identical), HNRNPF (31% identical), ESRP1 (24% identical), ESRP2 (24% identical), HNRNPH3 (22% identical), RBM12B (17% identical), RBM12 (15% identical).
Diseases named in the same sentence as GRSF1 in open-access papers:
GRSF1 is named in the same sentence as 28 diseases in open-access papers, as found by Europe PMC text mining. Sharing a sentence is not in itself a finding about the gene and the disease. The quoted sentences say what the papers report.
cervical cancer (6 papers, 2019 to 2025). A primary or metastatic malignant neoplasm involving the cervix. "Previous studies have indicated that GRSF1 promotes malignant phenotypes such as cell proliferation, migration, and invasion of gastric, liver, and cervical cancer." (PMID 40722682, 2025). "Similar to our results, GRSF1 has been found to be upregulated in cervical cancer and involved in oncogenic activity by regulating miR-G-10 or MIR-G-1." (PMID 34998399, 2022). "GRSF1 drives the metastasis of cervical cancer cells via the PIK3R3/AKT/NF-κB and TIMP3/MMP9 pathways." (PMID 34998399, 2022). "MIR‐G‐1 upregulates TMED5 and lamin B1 (LMNB1) in a GRSF1‐dependent manner and promotes malignant behavior and nuclear autophagy in the cervical cancer cells." (PMID 31418958, 2019). "In addition, GRSF1 participates in the miR-346-mediated promotion of the malignant phenotype of cervical cancer cells by enhancing AGO2." (PMID 34998399, 2022). "In addition, GRSF1 was revealed to promote cervical cancer by enhancing TMED5 and LMNB1 expression." (PMID 34998399, 2022). "Yang Z et.al GRSF1-mediated MIR-G-1 promotes EMT by directly increasing TMED5 and LMNB1 in cervical cancer cells." (PMID 33109773, 2020).
viral infection (3 papers, 2016 to 2023). "GRSF1 has been implicated in a number of physiological processes (e.g. embryogenesis, erythropoiesis, redox homeostasis, RNA metabolism) but also in the pathogenesis of viral infections and hyperproliferative diseases." (PMID 36494688, 2022). "GRSF1 participates in mitochondrial RNA metabolism, erythropoiesis, viral infection, cell senescence, etc., and its function in the blood coagulation process has never been reported." (PMID 37923734, 2023). "GRSF1 localizes in the nucleus, cytoplasm and mitochondria, and is involved in various biological processes such as mitochondrial RNA processing and trafficking, mitochondrial ribosome biosynthesis, erythropoiesis, redox homeostasis, and viral infection." (PMID 37923734, 2023). "To date, there are over 50 published studies on GRSF1 implicating this RNA binding protein in a number of physiological processes including RNA processing, redox homeostasis, embryo development, brain development erythropoiesis, stem cell differentiation, carcinogenesis and in viral infections." (PMID 36494688, 2022). "In the search for the miR-101 target gene, two genes were discovered that were involved in the process of viral infection: ATP5B22 and GRSF1, which promotes HSV-1 replication." (PMID 26984403, 2016). "The related report also demonstrated that GRSF1 interacts with the specific sequences AGGU and AGGGU within the influenza viral 5′UTR to selectively promote viral mRNA translation and virus infection." (PMID 26984403, 2016).
breast carcinoma (2 papers, 2021 to 2026). "Using breast cancer cell lines and tissue samples, we confirmed that GRSF1 was significantly up-regulated and MAPT was down-regulated in the tamoxifen-resistant group compared with the tamoxifen-sensitive group." (PMID 34406386, 2021). "Subsequent survival analysis showed that high expression of GRSF1 predicted poor prognosis, whereas MAPT was associated with favorable survival outcomes in TCGA breast cancer patients." (PMID 34406386, 2021). "GRSF1: While reported to promote tumor progression via the PI3K/AKT pathway in gastric and breast cancer.this research newly demonstrates its downregulation in cSCC and suggests a potential association with immune infiltration." (PMID 41438693, 2026). "The data of these independent experiments therefore verified the hypotheses generated using bioinformatics analysis, indicating that GRSF1 and MAPT might play a vital role in tamoxifen resistance in breast cancer." (PMID 34406386, 2021).
colon cancer (2 papers, 2024 to 2025). "Additionally, the expression of GRSF1 was examined in colon cancer cell lines using qPCR and phenotypically verified by in vitro experiments." (PMID 38947396, 2024). "GRSF1 showed strong staining in colon cancer tissues, while no expression was detected in normal endothelial cells." (PMID 40959429, 2025).
duodenal adenocarcinoma (2 papers, 2025). A carcinoma that arises from glandular epithelial cells of the duodenum. "GRSF1 was highly expressed in duodenal adenocarcinoma tissues compared with adjacent normal tissues (Appendix B Figure A2d)." (PMID 40722682, 2025). "In summary, Linc01559 may influence the malignant phenotype of duodenal adenocarcinoma cells by regulating GRSF1 expression." (PMID 40722682, 2025). "The results suggested that GRSF1 may play a tumor-promoting role in duodenal adenocarcinoma under acidic conditions and is regulated by Linc01559." (PMID 40722682, 2025).
gastric cancer (2 papers, 2021 to 2025). A primary or metastatic malignant neoplasm involving the stomach. "A recent study demonstrated that GRSF1 drives tumorigenesis and EMT-mediated metastasis in gastric cancer by activating the PI3K/AKT pathway, and may also facilitate immune evasion through modulation of the tumor immune microenvironment." (PMID 40959429, 2025).
age (1 paper, 2023). A temporal measurement of the time period elapsed since an identifiable point in the life cycle of an organism. "Moreover, our findings also suggest that GRSF1 might be a novel diagnostic marker or even a new target for the prevention or treatment of age-associated hypercoagulability, cardiovascular, cerebrovascular, and thrombotic diseases." (PMID 37923734, 2023).
anemia (1 paper, 2022). A reduction in the number of red blood cells, the amount of hemoglobin, and/or the volume of packed red blood cells. "If this effect may be of in vivo relevance and if there are no sufficient compensation reactions we reasoned that our Grsf1−/− mice would suffer from anemia." (PMID 36494688, 2022).
Azoospermia (1 paper, 2014). Absence of any measurable level of sperm,whereby spermatozoa cannot be observed even after centrifugation of the semen pellet. "Activation of mTOR results in translation of the RNA binding protein Dazl (Deleted in azoospermia-like), and Dazl subsequently binds the 3′UTR of Grsf1 to enhance translation." (PMID 25184340, 2014).
colon adenocarcinoma (1 paper, 2025). "This process yielded a four-gene signature—PDSS2, GRSF1, SLC39A8, and P4HA1—with significant prognostic value in colon adenocarcinoma." (PMID 40959429, 2025).
duodenal cancer (1 paper, 2025). "GRSF1 expression was significantly elevated in duodenal cancer tissues compared with normal tissues and was associated with tumor stemness, invasion, and apoptosis." (PMID 40722682, 2025). "High expression of Linc01559 and GRSF1 in duodenal cancer tissues indicates an increased risk of tumor recurrence and metastasis, suggesting that GRSF1 may represent a potential therapeutic target for duodenal cancer." (PMID 40722682, 2025). "Migration assays confirmed that GRSF1 overexpression increased the migratory ability of duodenal cancer cells, whereas Linc01559 knockdown significantly attenuated this effect." (PMID 40722682, 2025). "Apoptosis assays revealed that GRSF1 overexpression inhibited the apoptosis of duodenal cancer cells, which aligned with the previous findings that showed increased duodenal cancer cell apoptosis following Linc01559 knockdown." (PMID 40722682, 2025). "It was further revealed that Linc01559 promotes the malignant phenotype of duodenal cancer cells through its interaction with GRSF1." (PMID 40722682, 2025). "However, the upstream regulatory mechanisms governing GRSF1 in duodenal cancer remain unclear." (PMID 40722682, 2025).
hepatocellular carcinoma (1 paper, 2022). A malignant tumor that arises from hepatocytes. "The detailed biological effect and underlying mechanisms of the RBP GRSF1 in hepatocellular carcinoma (HCC) remain unclear." (PMID 34998399, 2022).
hypercoagulability (1 paper, 2023). "In this study, we found that GRSF1 could antagonize the age-associated hypercoagulability via posttranscriptional regulation of fibrinogen expression, and revealed GRSF1 as an endogenous negative regulator of fibrinogen plasma level and blood coagulation activity." (PMID 37923734, 2023). "Functionally, we show that GRSF1 overexpression in the liver decreases plasma fibrinogen levels and reduces hypercoagulability in old mice." (PMID 37923734, 2023). "Altogether, we suggest that the decrease of GRSF1 expression level in the liver during animal aging at least partially contributes to the increase of fibrinogen plasma level and hypercoagulability." (PMID 37923734, 2023). "Therefore, the reduction of hypercoagulability is solely attributed to the GRSF1 overexpression specifically suppresses fibrinogen expression in old mice liver." (PMID 37923734, 2023). "Moreover, we confirmed hypercoagulability and the decrease of GRSF1 expression level during mice aging." (PMID 37923734, 2023). "Altogether, these results imply that AAV9-mediated GRSF1 overexpression in aged mice liver specifically mitigates fibrinogen plasma level and may reduce age-associated hypercoagulability without exerting an off-target effect on other blood factors." (PMID 37923734, 2023). "GRSF1 overexpression in old mice liver specifically decreased fibrinogen plasma level and attenuated hypercoagulability in vivo without affecting other blood factors." (PMID 37923734, 2023). "Here, we report that GRSF1 attenuates hypercoagulability via negative modulation of fibrinogen expression." (PMID 37923734, 2023).
influenza infections (1 paper, 2016). "GRSF1 has been implicated in influenza infection, embryonic brain development and the regulation of apoptosis." (PMID 26984403, 2016). "GRSF1 has been implicated in influenza infections as a positive-acting translational regulatory factor by binding to the 5′UTRs of influenza RNAs." (PMID 26984403, 2016).
liposarcoma (1 paper, 2019). A usually painless malignant tumor that arises from adipose tissue. "Adriamycin-induced senescent human skin fibroblasts and doxorubicin-induced senescent liposarcoma cells also showed lower GRSF1 mRNA levels by 1.5 and 1.3-fold, respectively." (PMID 30944385, 2019).
myocardial ischemia (1 paper, 2022). A disorder of cardiac function caused by insufficient blood flow to the muscle tissue of the heart. "Collectively, our study revealed the pathogenesis of oxidative stress and ferroptosis associated with myocardial ischemia, and indicated the antioxidant and anti-ferroptosis effects of GEN on preventing myocardial injury by activating the Grsf1/GPx4 axis, serving as a potential therapeutic target." (PMID 35600863, 2022).
tumor (7 papers, 2017 to 2026). "An analysis of the relationships between GRSF1 and tumor stem cell markers revealed significant positive associations with UBE2K, XRCC5, SNRPD3, and CDC123 (Appendix B Figure A2c), which was consistent with previous findings." (PMID 40722682, 2025). "A GSEA revealed that GRSF1 participates in pathways associated with tumor malignancy." (PMID 40722682, 2025). "Knocking down GRSF1 expression reduced the expression of these markers and inhibited the ability of the acidic environment to enhance tumor stem cell self-renewal, as evidenced by decreased pellet formation (d and Appendix B Figure A2f)." (PMID 40722682, 2025). "Functional experiments were performed to verify the relationship between Linc01559, G-rich sequence binding factor 1 (GRSF1), and tumor malignant phenotype." (PMID 40722682, 2025). "From a functional point of view, YY1 overexpression rescued the tumor-inhibiting effect of decreased GRSF1 on HCC cell proliferation, apoptosis, colony formation and migration (p<0.05)." (PMID 34998399, 2022). "In this study, we uncovered that miR-30e-5p acts as a tumor suppressor in HCC by regulating YY1 as an upstream regulator competing with GRSF1." (PMID 34998399, 2022). "This study identified YY1 as an essential downstream effector of GRSF1 and rescued the tumor-inhibiting effect of GRSF1 knockdown, suggesting that GRSF1 promotes hepatocarcinogenesis by promoting YY1 expression." (PMID 34998399, 2022). "Xenograft tumors derived from MHCC-97H cells cotransfected with pre-miR-30e-5p and over-GRSF1 exhibited larger tumor sizes (pre-miR-30e-5p+ov-GRSF1 group) than those in the premiR-3pe-5p group (p<0.05), supporting our in vitro results." (PMID 34998399, 2022). "Studies have indicated that dysregulated GRSF1 contributes to tumor progression." (PMID 40722682, 2025). "Furthermore, chi-square tests suggested that GRSF1 upregulation was positively correlated with larger tumor size (p<0.01), worse differentiation (p<0.05), microscopic vascular invasion (p<0.01) and advanced TNM stage in HCC (p<0.01)." (PMID 34998399, 2022). "In addition, xenograft tumors derived from MHCC-97H cells cotransfected with pre-miR-30e-5p and sh-GRSF1 exhibited even smaller tumor sizes (pre-miR-30e-5p+sh-GRSF1 group) than those derived from cells transfected with pre-miR-30e-5p alone (pre-miR-30e-5p group)." (PMID 34998399, 2022). "In addition, a xenograft model in immunodeficient mice showed that tumors derived from MHCC-97H cells with decreased GRSF1 expression resulted in smaller tumor sizes (sh-GRSF1 group) and that YY1 overexpression (sh-GRSF1+ov-YY1 group) promoted tumor growth (p<0.05)." (PMID 34998399, 2022). "Specifically, PDSS2, GRSF1, SLC39A8 and P4HA1 were significantly upregulated in tumor tissues compared to normal samples." (PMID 40959429, 2025). "Specifically, analysis of proteomic data from the Human Protein Atlas (HPA) revealed that PDSS2, GRSF1, SLC39A8, and P4HA1 are markedly upregulated in tumor tissues compared to normal samples." (PMID 40959429, 2025). "The identification of hub genes like GRSF1 and UQCRFS1 and their link to favorable metabolic profiles offers novel insights into tumor neovascularization and metastasis, with significant clinical implications for targeting metabolic pathways in CRC therapy." (PMID 38947396, 2024). "qRT–PCR assays demonstrated that GRSF1, YY1 and Ki67 expression was decreased in the VE821 group xenograft tumor tissue, while miR-30e-5p expression was increased (p<0.01)." (PMID 34998399, 2022). "Immunohistochemistry assays showed that GRSF1, YY1 and Ki67 expression was decreased in the VE821 group tumor tissue (p<0.05)." (PMID 34998399, 2022).
infection (3 papers, 2022 to 2024). The state of being infected such as from the introduction of a foreign agent such as serum, vaccine, antigenic substance or organism. "Lastly, we characterized the effect of GRSF1 KD on viral mRNA during infection." (PMID 36253464, 2022). "To investigate whether GRSF1 knockdown has an effect on hemostasis, we first analyzed the tail bleeding time and clotting time after 8.5 weeks of AAV9 infection." (PMID 37923734, 2023). "It is not known whether avian IAVs utilize GRSF1 during infection in avian hosts." (PMID 39066299, 2024).
cancer (2 papers, 2019 to 2021). A tumor composed of atypical neoplastic, often pleomorphic cells that invade other tissues. "At present, only a small number of studies have focused on the role of GRSF1 in cancer." (PMID 34406386, 2021).
infectious disease (1 paper, 2025). A disorder directly resulting from the presence and activity of a microbial, viral, or parasitic agent in humans. "While no GO terms were found to be significantly enriched in these upregulated genes, the upregulation of GRSF1 is noteworthy due to its association with infectious disease pathways." (PMID 40989927, 2025).
GRSF1 also shares sentences with these, for which no sentence is quoted: colorectal cancer (2 papers); myocardial infarction (2); Obesity (1); osteosarcoma (1); Perrault syndrome (1); thrombotic disease (1); triple-negative breast carcinoma (1); tuberculosis (1).